PDCD1LG2 (programmed cell death 1 ligand 2)
Description:
Plays a critical role in induction and maintenance of immune tolerance to self. Acts as a ligand for the inhibitory receptor PDCD1/PD-1, inhibiting T-cell proliferation by blocking cell cycle progression and cytokine production.
Synonyms: PD-L2; B7-DC; CD273; B7DC; PDCD1L2; PDL2; Btdc; bA574F11.2
Tractability: Antibody: a drug acting on it is in phase 1 trials; UniProt places it where antibodies can reach, with high confidence; its Gene Ontology location is reachable by antibodies, with high confidence; UniProt predicts a signal peptide or a membrane-spanning region. PROTAC: a small molecule that binds it is known.
Gene: Protein-coding gene on chromosome 9 (5,510,491 to 5,571,282, forward strand). Ensembl gene ENSG00000197646.
Subcellular location: Secreted (Isoform 3); Endomembrane system (Isoform 2); Cell membrane (Isoform 1)
Subcellular location (Human Protein Atlas): Cytosol; Predicted to be secreted
Pathways (Reactome):
Immune System: Co-inhibition by PD-1; PD-L1(CD274) glycosylation and translocation to plasma membrane
Gene Ontology:
Molecular function: protein binding; receptor ligand activity
Biological process: negative regulation of activated T cell proliferation; negative regulation of interleukin-10 production; negative regulation of T cell activation; negative regulation of T cell receptor signaling pathway; negative regulation of type II interferon production; cell surface receptor signaling pathway; cellular response to lipopolysaccharide; immune response; negative regulation of T cell proliferation; positive regulation of T cell proliferation; T cell costimulation
Cellular component: endomembrane system; plasma membrane; external side of plasma membrane; extracellular region
Genetic constraint (gnomAD): Loss-of-function variants: 27 observed, 24.54 expected, observed/expected ratio (o/e) 1.1, 90% interval 0.81 to 1.52. The upper end of that interval is the gene's LOEUF score, 1.52, which puts it in group 6 of 6, group 1 being the genes least tolerant of losing a copy. Missense variants: 336 observed, 297.06 expected, observed/expected ratio (o/e) 1.13, 90% interval 1.03 to 1.24. Synonymous variants: 102 observed, 113.72 expected, observed/expected ratio (o/e) 0.9, 90% interval 0.76 to 1.06.
Cancer hallmarks: suppression of growth (promotes)
Homologues: Orthologues: macaque PDCD1LG2 (96% identical), chimpanzee PDCD1LG2 (88% identical), pig PDCD1LG2 (69% identical), dog PDCD1LG2 (67% identical), rat Pdcd1lg2 (65% identical), mouse Pdcd1lg2 (63% identical), tropical clawed frog pdcd1lg2 (32% identical), zebrafish si:ch211-241b2.5 (27% identical). Paralogues in human: CD274 (33% identical), CD80 (19% identical), CD86 (16% identical), RFPL2 (7% identical), RFPL3 (7% identical), RFPL1 (6% identical), RFPL4A (6% identical), RFPL4AL1 (6% identical), RNF135 (6% identical), RFPL4B (4% identical), SPRYD4 (3% identical), RNF152 (2% identical).
Diseases named in the same sentence as PDCD1LG2 in open-access papers:
PDCD1LG2 is named in the same sentence as 305 diseases in open-access papers, as found by Europe PMC text mining. Sharing a sentence is not in itself a finding about the gene and the disease. The quoted sentences say what the papers report.
melanoma (127 papers, 2014 to 2025). A malignant, usually aggressive tumor composed of atypical, neoplastic melanocytes. "PD-L1 and PD-L2 cell surface expression were significantly correlated with the CD274 (PD-L1) and PDCD1LG2 (PD-L2) transcript expression in the nine melanoma cell lines with matched transcriptome data." (PMID 34073253, 2021). "Individual immunotherapy panel markers CD274, PDCD1LG2, CD8A, IRF1 and a combined L1/L2 mRNA levels show promising associations with melanoma immunotherapy outcome." (PMID 31533832, 2019). "So far, the epigenetic regulation with particular focus on DNA promoter methylation of the PD-L2 encoding gene, PDCD1LG2, has not been considered as a biomarker in the context of anti-PD-1 immunotherapies in melanoma." (PMID 32586358, 2020). "We developed a targeted MS platform to quantify programmed cell death-1 (PD-1), programmed cell death 1 ligand 1 (PD-L1), and programmed cell death 1 ligand 2 (PD-L2) at fmol/microgram protein levels in formalin fixed, paraffin-embedded sections from 22 human melanomas." (PMID 28546465, 2017). "Moreover, our survey identified a differentially methylated side within the promoter of PD-L2 (PDCD1LG2) that may predict progression-free survival in melanoma patients receiving anti-PD-1 immunotherapy." (PMID 38386085, 2024). "However, patients with PD-L1-negative melanomas can respond to anti-PD-1 blockade, suggesting that the other PD-1 ligand, PD-L2 (programmed cell death 1 ligand 2), might also be relevant for efficacy of PD-1 inhibition." (PMID 32586358, 2020). "Consistent with the phenotype of CD163+ TAMs in the melanoma TME, moTAMs expressed the genes involved in immune suppression, including CD274 (PD-L1), PDCD1LG2 (PD-L2), and TGFB1." (PMID 38903497, 2024). "To assess the mRNA expression of four immunotherapy markers, CD274, PDCD1LG2, CD8A and IRF1, we used a multiplex RT-qPCR immunotherapy panel on the GeneXpert platform in melanoma patients treated with anti-PD-1 therapy." (PMID 31533832, 2019). "Considering that CYTL1 may be a potential oncogene in melanoma, it was assessed how CYTL1 interacted with PDCD1, CD274, HAVCR2, TIGIT, SIGLEC15, CTLA4, LAG3, and PDCD1LG2." (PMID 37745303, 2023). "The cell surface protein expression patterns of these markers in our melanoma panel did not precisely reflect their transcript expression patterns in the human SKCM dataset of TCGA (n = 472), although both protein and transcript expression of PD-L2 (PDCD1LG2) and HLA-DR (HLA-DRA) were correlated." (PMID 29977240, 2018).
glioma (81 papers, 2018 to 2025). A benign or malignant brain and spinal cord tumor that arises from glial cells (astrocytes, oligodendrocytes, ependymal cells). "After that, we found that 6 immune checkpoints (CD274, CTLA4, LAG3, LGALS9, PDCD1, and PDCD1LG2) were significantly upregulated in the high-glioma-risk group, while RDH5, RDH10 and DHRS3 simultaneously have a substantial positive connection with PDCD1LG2." (PMID 39465792, 2024). "All six of the most critical ICGs that were examined, including CD274, CTLA4, HAVCR2, IDO1, PDCD1, and PDCD1LG2, exhibited a significant positive correlation with the risk scores in glioma samples." (PMID 36845382, 2023). "In TCGA datasets, there was positive correlation between PDIA5 and CD276 or PDCD1LG2 in pan-glioma patients, and PDIA5 expression was positively associated with CD276, PDCD1LG2 and HAVCR2 in LGG patients." (PMID 33664747, 2021). "The high-risk group presented a higher expression of PD1 (PDCD1), CTLA4, PD-L1 (CD274), and PD-L2 (PDCD1LG2), and our risk signature could also distinguish glioma patients with similar expression levels of immune checkpoints." (PMID 37004060, 2023). "Wang reported that PDCD1LG2 in gliomas was closely related to inflammation and immune responses and was associated with better survival." (PMID 40725113, 2025). "Immune checkpoint genes such as PD-L1, PD-1, CTLA4, LAG3, HAVCR2, PDCD1LG2 were positively correlated with IGFBP5 in glioma." (PMID 38164271, 2024). "We also found that the HIS subtype had the highest expression of several immune checkpoints (particularly IDO1, CD274 and PDCD1LG2), it means that glioma samples from HIS subtype tend to be immunosuppressed." (PMID 38613347, 2024). "In general, gliomas had lower transcript expression of SIRPA (gene encoding SIRPalpha) and higher of PD-L1 (CD274), PD-L2 (PDCD1LG2), TIM-3 (HAVCR2), PD-1 (PDCD1) (respectively)." (PMID 36768201, 2023). "We further explored the relationship between ITGA5 and some immune checkpoints, such as PDCD1 (PD-1), CD274 (PD-L1), and PDCD1LG2 (PD-L2) in gliomas based on the TCGA dataset." (PMID 35371978, 2022). "Results refer thatMLLT11 had a highly negative correlation with PDCD1, PD-L1, TIM3(HAVCR2), and PD‐L2 (PDCD1LG2) in grade 3 glioma analysis." (PMID 36033495, 2022). "In CGGA dataset, PDIA5 expression was positively associated with CD276, CD274, PDCD1LG2, and HAVCR2 in pan-glioma and LGG patients, and positively correlated with CD276, PDCD1, CD274, PDCD1LG2, and HAVCR2 in GBM patients." (PMID 33664747, 2021). "Notably, we also found that 6 immune checkpoints were significantly upregulated in the high-glioma-risk group, including CD274, CTLA4, LAG3, LGALS9, PDCD1, and PDCD1LG2." (PMID 39465792, 2024). "Altogether, these findings suggested that glioma patients might benefit from HAVCR2- or PDCD1LG2-based immunotherapies." (PMID 35198632, 2022). "However, the single cell RNA sequencing results showed that CD274 and PDCD1LG2 were not only expressed in malignant cells, but were also heavily expressed in immune cells in gliomas." (PMID 34100771, 2021). "In addition, as the expression of NUP37 was highly positively correlated with the genes encoding PD‐L1 (CD274) and PD‐L2 (PDCD1LG2), it is more importantly that PD‐L1 and PD‐L2 are an immune checkpoint inhibitor in gliomas." (PMID 34264013, 2021). "Our data revealed a significant correlation between the expression levels of immune checkpoint molecules (CD274, CTLA4, HAVCR2, LAG3, PDCD1, PDCD1LG2, TIGIT, and SIGLEC15) and RAB32 in high-grade gliomas (HGG)." (PMID 39668831, 2024). "Assessments of the immune blockade response to 3 checkpoints (PDCD1, CD274, and PDCD1LG2) and the IC50 for 2 classical antitumor drugs were conducted for glioma samples with varying SOCS1 expression levels in the CGGA and TCGA databases." (PMID 39654174, 2024). "In general, most immune checkpoints (including PD-1, TIM-3, CD96, PDCD1, IDO1, PDCD1LG2, and CTLA-4) were highly expressed in glioma cells." (PMID 36778644, 2023).
glioma (continued). "MAPK4 expression was significantly positively correlated with expression of the main immunoinhibitory checkpoint molecules PD‐1, PD‐L1, HAVCR2, PDCD1LG2 and TIGIT in glioma." (PMID 36999945, 2023). "We further analyzed the expression distribution of immune checkpoints gene (including CD274, CTLA4, HAVCR2, LAG3, PDCD1, PDCD1LG2, TIGIT, and SIGLEC15) in glioma tissues and normal brain tissues using the TCGA database." (PMID 36915038, 2023). "We investigated the immune checkpoint expression in glioma specimens and uncovered that CD274 (PD-L1), PDCD1, PDCD1LG2, CTLA4, CD276, HAVCR2, and LAG3 were significantly overexpressed in the high DDR score subtype." (PMID 35720326, 2022). "ALKBH5 expression showed positive association with ICP receptors such as TNFRSF14, CD40, CD96 and CD200R1, and ICP ligands such as PDCD1LG2, CD70, TNFSF14, ICOSLG and CD274 in glioma tissues." (PMID 35444654, 2022). "It is found that the expression of PROS1 had positive correlations with PD-1, PD-L1, PDCD1LG2, CTLA4, HAVCR2, and GZMB (all P <0.05) in glioma." (PMID 36685506, 2022). "The highest expression was detected in the WHO glioma grade IV tumors (CD274 p = 2.0e − 08, HAVCR2 p = 1.5e − 09, LAG3 p = 9.7e − 05, PDCD1 p = 5.6e − 05, PDCD1LG2 p = 2.2e − 18, and SIGLEC15 p = 4.3e − 05)." (PMID 35198632, 2022). "B2M exhibited a highly positive correlation with immune checkpoint molecules, such as PDCD1LG2, HAVCR2, CD274 in pan-gliomas and LGG samples, respectively." (PMID 33658560, 2021). "TOX had high correlation with CD276, IDO1, PDCD1LG2, and VTCN1 in both pan-glioma analysis and GBM alone." (PMID 32762688, 2020). "TOX was strongly correlated with CD276, IDO1, PDCD1LG2 (PD-L2), and VTCN1 in pan-glioma analysis and GBM alone in both TCGA and CGGA cohorts." (PMID 32762688, 2020). "PDIA3 was highly positively correlated with HAVCR2, CD274, PDCD1LG2 and others in pan-gliomas and LGG and GBM samples, and PDIA3 demonstrated a high positive correlation with PDCD1LG2 in GBM." (PMID 32687065, 2020). "Specifically, we found that, as IGFBP5 levels increased, the expression of the seven immune checkpoint genes (BTLA, CD274, CTLA4, HAVCR2, LAG3, PDCD1, and PDCD1LG2) were increased and a large positive correlation was observed between IGFBP5 and these immune checkpoints in glioma." (PMID 38164271, 2024). "Indeed, the expression of A3C displayed positive correlations with CD274, PDCD1, PDCD1LG2, SIGLEC15, CTLA4, HAVCR2, and GZMB in glioma (P < 0.05)." (PMID 37809064, 2023). "Through analysis of glioma samples in the CGGA and TCGA databases, we found that CDCA7 expression level was significantly correlated with tumor-related immunosuppressive molecules, including CD80, CD276, CD28, PDCD1LG2, and TNFSF4." (PMID 37510310, 2023). "All eight immune checkpoint genes were overexpressed in both GBM and LGG tumors, of which only HAVCR2 was significantly upregulated in both glioma types and PDCD1LG2 showed significant upregulation in GBM but not in LGG (p < 0.05)." (PMID 35198632, 2022). "Gliomas with a high TME-score expressed more immune checkpoints, such as LAG3, CD40, and PDCD1LG2." (PMID 34489938, 2021). "Based on TCGA and CGGA datasets, we observed a high and positive correlation between TNFSF13 and PDCD1LG2, HAVCR2, CTLA4, and other checkpoint molecules in pan-gliomas, LGG and GBM analysis, and TNFSF13 expression is tightly correlated with HAVCR2 in glioblastomas." (PMID 34712225, 2021). "Therefore, we hypothesized that high ALKBH5 expression altered the immune microenvironment in the glioma tissues by modulating the expression levels of ICP receptors and ligands such as TNFRSF14, CD40, CD96, PDCD1LG2, CD70 and TNFSF14." (PMID 35444654, 2022).
glioma (continued). "Thus, coexpression of CD44 and checkpoint family members were checked in glioma, and we found that CD44 expression positively correlates with the expression level of PD-L1 and PD-1 and correlates with the expression level of PDCD1LG2 (namely PD-L2) as well in the TCGA and CGGA glioma datasets." (PMID 35187044, 2021). "In TCGA datasets, among WHO grade 3 glioma,MLLT11 showed a highly negative correlation with PD-1 (r = -0.34, p = 8.3 × 10-28), PD-L1 (r = -0.41, p = 3.5 × 10-11), TIM3(HAVCR2) (r = -0.4, p = 1.2 × 10-11), and PD‐L2 (PDCD1LG2) (r = -0.58, p < 2.2 × 10-16)." (PMID 36033495, 2022).
breast cancer (71 papers, 2014 to 2026). A primary or metastatic malignant neoplasm involving the breast. "The tumor samples were assembled into standard core-based tissue microarrays (TMAs) and IF-IHC was performed for breast cancer relevant proteins including nuclear protein Ki-67, Programmed cell death 1 ligand 2(PD-L2), and Progesterone receptor (PR)." (PMID 37481512, 2023). "The proposed algorithm was used to select optimal quantile biomarkers of breast cancer progression based on cancer cells’ cell signal intensity levels of nuclear protein Ki-67, Proliferating cell nuclear antigen, Programmed cell death 1 ligand 2, and Progesterone receptor." (PMID 37481512, 2023). "Moreover, the expression of LAG3, CTLA-4, PD-L1, CD274, TIGIT, HAVCR2 and PDCD1LG2 was upregulated in the TFRC high-expression group compared with the TFRC low-expression group in breast cancer." (PMID 35847985, 2022). "MiR-93 has been implicated as a potential immune regulator in breast cancer cells through targeting programmed death-ligand 1 (PD-L1)/cluster of differentiation 274 (CD274), programmed Cell Death 1 Ligand 2 (PDCD1LG2), and natural killer cell cytotoxicity receptor 3 ligand 1 (NCR3LG1)." (PMID 33918859, 2021). "We also noted that African ancestry was associated with a higher frequency of copy number alterations in CD274/JAK2/PDCD1LG2 (n = 150; OR = 1.56; FDR = 0.01), which was preferentially found in ER/HER2-negative breast cancer." (PMID 41162424, 2025).
lung carcinoma (52 papers, 2015 to 2026). "We next compared RNA expression of inhibitory ligands in publically available microarray data sets for CAFs from human tumour tissues and normal counterparts, and confirmed elevated PDCD1LG2 gene expression in human lung cancer." (PMID 29507342, 2018). "In addition, programmed death ligand 2 (PDCD1LG2) SNPs rs78096119 and rs12237624 are significantly related to tuberculosis infection, which is associated with lung cancer." (PMID 35525982, 2022). "This study aimed to identify novel single nucleotide polymorphisms (SNPs) of programmed death-1 (encoded by PDCD1) and its ligands, programmed death ligand 1 (CD274) and 2 (PDCD1LG2), associated with lung cancer risk in never-smoking women." (PMID 34631591, 2021).
gastric cancer (50 papers, 2015 to 2025). A primary or metastatic malignant neoplasm involving the stomach. "CD274 and PDCD1LG2 encode PD-L1 and PD-L2, respectively, which suggests a potential role of PD-1/PD-L1 pathway inhibitors in the treatment of gastric cancer." (PMID 28434400, 2017). "The authors identified distinct mutations and epigenetic profiles (recurrent PIK3CA mutations, high DNA hypermethylation levels and amplification of JAK2, CD274 and PDCD1LG2) in EBV-associated gastric cancer cases." (PMID 28454117, 2017). "The TCGA study also revealed that the amplification of CD274 and PDCD1LG2 (also encoding PD-L1 and PD-L2) was enhanced in the EBV-positive gastric cancer subgroup." (PMID 27012666, 2016). "It should be noted that PLGRKT is located alongside JAK2, CD274 (PD-L1) and PDCD1LG2 (PD-L2) within the 9p24.1 locus that is commonly amplified in EBV-positive gastric cancers." (PMID 25613731, 2015). "Intriguingly, data from the TGCA gastric cancer dataset show that EBV-positive gastric cancer frequently exhibits amplification at 9p24.1, a locus containing CD274 and PDCD1LG2 (encoding PD-L1 and PD-L2), which is associated with a more immune-active profile." (PMID 40831929, 2025). "High THSD7A expression suppressed the sensitivity of patients with gastric cancer to drugs, such as 5-fluorouracil, bleomycin, and cisplatin, and upregulated immune checkpoints, such as HAVCR2, PDCD1LG2, TIGIT, and CTLA4." (PMID 37905960, 2023). "The immune checkpoint analysis indicated that gastric cancer patients with upregulated GGT5 expression showed a higher TIDE score and expression of CD274, CTLA4, HAVCR2, LAG3, PDCD1, PDCD1LG2, and TIGIT than patients in the GGT5-low expression group." (PMID 35368661, 2022). "We further demonstrated that SCRS data amplified by either MDA or MALBAC from a gastric cancer cell line could accurately detect gastric cancer CNVs with comparable sensitivity and specificity, including amplifications of 12p11.22 (KRAS) and 9p24.1 (JAK2, CD274, and PDCD1LG2)." (PMID 26251698, 2015).
lymphoma (47 papers, 2015 to 2025). A malignant (clonal) proliferation of B- lymphocytes or T- lymphocytes which involves the lymph nodes, bone marrow and/or extranodal sites. "To investigate germline predisposition in lymphoma, we performed whole-exome sequencing and discovered a novel variant (c.817-1G>T) in programmed cell death 1 ligand 2 (PD-L2) in a family with early-onset lymphomas and other cancers." (PMID 35613340, 2022). "Chromosome 9p24.1 includes the loci of CD274 (encoding the PD-L1 checkpoint) and PDCD1LG2 (encoding PD-L2), and structural variants (SVs) affecting this region have proven amongst the most reproducible indicators of ICI response in lymphoma." (PMID 41295262, 2025). "PD-L1 (CD274) and PD-L2 (PDCD1LG2 or CD273) are variably expressed by malignant lymphoma cells and are the cognate ligands for PD-1 expressed on CTLs." (PMID 33804869, 2021). "We examined the 19 cases with associated SVs for fusions involving either CD274 or PDCD1LG2, and we identified a putative fusion transcript for RNF38->PDCD1LG2 involving three cases, all of which were lymphoma." (PMID 32024823, 2020).
head and neck squamous cell carcinoma (43 papers, 2016 to 2025). A squamous cell carcinoma that arises from any of the following anatomic sites: lip and oral cavity, nasal cavity, paranasal sinuses, pharynx, larynx, and salivary glands. "PDCD1, PDCD1LG2 are the key targets in the treatment of widely used PD-1/PD-L1 inhibitors and plays an important role in adolescent idiopathic arthritis, diffuse large B-cell lymphoma, head and neck squamous cell carcinoma, colorectal cancer and other diseases." (PMID 33215029, 2020).